TMEM191C (transmembrane protein 191C)
Tractability: Antibody: UniProt predicts a signal peptide or a membrane-spanning region.
Gene: Protein-coding gene on chromosome 22 (21,466,423 to 21,471,269, forward strand). Ensembl gene ENSG00000206140.
Subcellular location: Membrane
Gene Ontology:
Cellular component: membrane
Genetic constraint (gnomAD): Loss-of-function variants: 17 observed, 19.57 expected, observed/expected ratio (o/e) 0.87, 90% interval 0.59 to 1.3. The upper end of that interval is the gene's LOEUF score, 1.3, which puts it in group 5 of 6, group 1 being the genes least tolerant of losing a copy. Missense variants: 157 observed, 157.95 expected, observed/expected ratio (o/e) 0.99, 90% interval 0.87 to 1.13. Synonymous variants: 78 observed, 75.93 expected, observed/expected ratio (o/e) 1.03, 90% interval 0.86 to 1.24.
Homologues: Orthologues: macaque TMEM191C (95% identical), rat Tmem191c (65% identical), mouse Tmem191 (64% identical). Paralogues in human: TMEM191B (92% identical).